APOL1 (apolipoprotein L1)
Diseases named in the same sentence as APOL1 in open-access papers (continued):
Sharing a sentence is not in itself a finding about the gene and the disease.
Nephropathy (continued). "Thus, it is possible that the G1/G2 differences observed in this model apply more to interferon-induced disease than other presentations of APOL1-nephropathy." (PMID 34350953, 2021). "Not all humans with two copies of APOL1 risk variants develop kidney disease, suggesting that some other factor or factors (second hit) must also be present to cause kidney damage." (PMID 34350953, 2021). "In humans with APOL1-nephropathy, tissue biopsy analysis often reveals glomerulosclerosis." (PMID 34350953, 2021). "Many forms of APOL1-nephropathy involve viral infections or an inflammatory trigger, suggesting that immune mediators may function as a ‘second hit’." (PMID 34350953, 2021). "Because these transgenic mice model many different features of APOL1-nephropathies, i.e. proteinuria, sclerosis, kidney dysfunction, they will be useful for both identifying mechanisms of injury and testing therapeutic interventions at different stages of disease." (PMID 34350953, 2021). "The specific role of APOL1 protein in the development of HIVAN is still under investigation, however, poorly controlled HIV infection is the most potent susceptibility factor for APOL1-associated nephropathy that has been identified to date." (PMID 32915357, 2020). "This proinflammatory pathway represents a possible therapeutic target for APOL1 nephropathy." (PMID 32854642, 2020). "These were subsequently tested in an all-cause ESKD meta-analysis including 3787 all-cause ESKD cases and 6059 non-diabetic non-nephropathy controls of which APOL1 renal-risk-genotype carriers were excluded." (PMID 31092297, 2019). "The relative contributions of APOL1 protein and APOL1 RNA to APOL1 nephropathy remain uncertain." (PMID 30417125, 2018). "Transcript analysis of mouse kidney disease models, including folic-acid (FA)–induced nephropathy, unilateral ureteral obstruction (UUO), or apolipoprotein L1 (APOL1)-associated kidney disease, indicated that Jag1 and Notch2 levels were higher in all analyzed kidney fibrosis models." (PMID 30226866, 2018). "Apolipoprotein L1 (APOL1) gene is the other gene associated with CKD; it increases the risk of nephropathy induced by immunodeficiency syndrome, focal glomerulosclerosis, CKD associated with hypertension, and CKD unrelated to diabetes especially in the black population." (PMID 28975087, 2017). "Secondly, the high prevalence, in African American subjects, of genetic variants of the APOL1 gene, encoding apolipoprotein L1 (a component of HDL), may explain the high susceptibility to nephropathy, in particular to FSGS, of this ethnic group." (PMID 27973438, 2016). "The exact biological mechanism underlying this APOL1-associated nephropathy is not yet known but appears to be specific to the human variants." (PMID 27494254, 2016). "Previous studies have established that APOL1 kidney risk variants are strongly associated with kidney disease among adult AA; specifically, HIV-associated nephropathy (odds ratio, 29; 95% confidence interval, 13–68) and FSGS (odds ratio, 17; 95% confidence interval, 11–26)." (PMID 27900314, 2016). "In this sample largely free of CKD, a large proportion of individuals with early kidney damage were among those without high-risk APOL1 variants." (PMID 25884165, 2015). "One example is a study conducted in an Ethiopian population without HIV-associated nephropathy, which showed an absence of the APOL1 G1 and G2 risk alleles." (PMID 26112018, 2015). "Less is known about the relation of APOL1 and early kidney damage." (PMID 25884165, 2015). "Adjustment for the APOL1 G1 and G2 nephropathy risk variants marginalized but did not abolish the significant evidence of associations observed at three loci (Pemp<0.048; n = 5 SNPs)." (PMID 24551085, 2014).
Nephropathy (continued). "Among African-Americans, genome wide association revealed a strong correlation between the G1 and G2 alleles of APOL1 (apolipoproteinL1, also called trypanolytic factor) and kidney diseases including focal and segmental glomerulosclerosis, HIV-associated nephropathy and hypertensive nephrosclerosis." (PMID 23300552, 2012). "Therefore, the search for additional nephropathy susceptibility loci in AAs, conditional on other important loci (MYH9 and APOL1) remains critical." (PMID 21698141, 2011). "We conclude that variants in FRMD3 contribute to the risk for nephropathy in AA with T2DM, an effect that was observed only after accounting for MYH9 (and less so APOL1) gene variants and evaluating a subset of AA cases likely enriched for T2DM-associated nephropathy." (PMID 21698141, 2011). "Our analyses in 3263 AA T2DM-ESRD cases and non-diabetic, non-nephropathy controls revealed an approximate 25–30% increase in DN risk with multiple FRMD3 SNPs in subjects not homozygous for the MYH9 E1 risk haplotype (or APOL1 risk variants)." (PMID 21698141, 2011). "Stratified analyses based on the chromosome 22 nephropathy risk haplotypes demonstrated that FRMD3 variants were associated with diabetic nephropathy risk in cases without two MYH9 (or APOL1) risk haplotypes." (PMID 21698141, 2011). "Currently, there are no approved disease-specific therapies for APOL1-associated nephropathy." (PMID 39271961, 2024). "The development of effective treatment options for APOL1-associated nephropathies has been hampered by the lack of efficient animal model systems to study their pathogenesis and to perform reliable and cost-effective screenings for potential therapeutic targets." (PMID 37925499, 2023). "This latter point may explain why some patients with FSGS did not exhibit high APOL1 expression, because the underlying kidney disease may not have been APOL1 nephropathy." (PMID 37927001, 2023). "After adjusting for age, sex, and African ancestry proportion, authors found that the presence of JCV viruria in patients with increased risk of APOL1-associated nephropathy (2 APOL1 risk variants) was negatively associated with albuminuria and CKD (eGFR <60 mL/min/1.73 m2)." (PMID 34457361, 2021). "This pathway may represent a novel therapeutic target for APOL1 nephropathy." (PMID 32854642, 2020). "FIND (Family Investigation of Nephropathy and Diabetes) study group found that α-actinin-4 polymorphism could interact with APOL1 SNPs with regard to the risk of non-DM related ESRD in African Americans." (PMID 26881045, 2016). "Therefore it is plausible that disruption of this region of the protein may either prohibit proper binding of APOL1 to its usual partners, or perhaps permit new interactions that induce nephropathy." (PMID 26147622, 2015). "APOL1 G1 and G2 alleles in the homozygous or compound heterozygous state (G1/G1, G1/G2 or G2/G2) confer protection against Trypanosoma brucei gambiense infection but also increase susceptibility to nephropathy in non-trypanosomiasis endemic areas, especially in the presence of HIV infection." (PMID 33116287, 2020). "It is likely that the interplay between APOL1 and several modifiable environmental factors or interactive genes such as NPHS2, SDCCAG8, and BMP4 produces the variable spectrum of APOL1 nephropathy." (PMID 26156092, 2015). "In addition, relationships between APOL1 G1/G2 nephropathy risk variants and non-muscle MYH9 risk variants (E1 risk haplotype) and SCT were assessed to determine whether interactions between these genes were present." (PMID 26592908, 2015). "Several transgenic mouse models have been developed to study APOL1-nephropathy, but none of these models develop both the proteinuria and the histologic lesions observed in humans in response to a known trigger." (PMID 34350953, 2021). "The development of mouse models for APOL1-nephropathy has been challenging owing to the fact that APOL1 is not present in mice." (PMID 34350953, 2021).
Nephropathy (continued). "A secondary analysis was performed excluding APOL1 renal-risk-genotype carriers in T2D-ESKD cases and non-diabetic non-nephropathy controls (APOL1-negative model) to enrich for T2D-associated ESKD." (PMID 31092297, 2019). "We also observed a significant increase in myh9 expression in APOL1 G1/atpif1α-MO vs. APOL1 G1 injected embryos, however, neither of these conditions induced nephropathy." (PMID 26147622, 2015). "Compelling statistical evidence in human cohorts points to the G1 and G2 alleles of APOL1, rather than MYH9 variation, as the most likely contributors to nephropathy risk." (PMID 26147622, 2015). "Fine mapping studies reveal that several independent SNPs and regions in and near the apolipoprotein L1 gene (APOL1) and non-muscle myosin heavy chain 9 gene (MYH9) are associated with nephropathy susceptibility." (PMID 21698141, 2011). "MYH9 and APOL1 are strongly associated with non-diabetic ESRD in AAs and can potentially limit ability to detect other nephropathy susceptibility genes with weaker effect." (PMID 21698141, 2011). "For this reason, it has been proposed that these diseases may be included as part of an APOL1 nephropathy spectrum rather than being considered distinct entities in individuals with the high-risk genotype." (PMID 35207681, 2022). "Continued work to understand the connection between innate immune signaling events and APOL1 gene expression will be important to understand both viral and nonviral triggers for FSGS in the APOL1 nephropathies." (PMID 37927001, 2023). "A total of 664 T2D-ESKD cases and 918 non-diabetic non-nephropathy controls were excluded from stage 1 analysis, leaving 2768 T2D-ESKD cases and 6059 controls in the APOL1-negative model." (PMID 31092297, 2019).
Hypertension (80 papers, 2012 to 2026). The presence of chronic increased pressure in the systemic arterial system. "The outcome of these APOL1-associated pregnancy complications frequently results in prematurity and low birth weight, both of which are known risk factors for hypertension and kidney disease later in life due to reduced nephron endowment." (PMID 40940784, 2025). "Having high-risk APOL1 alleles and hypertension at the time of study enrollment decreased the likelihood of achieving sustained proteinuria remission off treatment." (PMID 39729127, 2025). "Black women are at particularly high risk for PE, potentially due to higher rates of hypertension and cholesterol, compounded by healthcare disparities and possible genetic factors, such as the APOL1 gene." (PMID 40004721, 2025). "CKD stage, high-risk APOL1 alleles, hypertension stage, and education all significantly impacted the likelihood of progression to the composite eGFR decline outcome." (PMID 39729127, 2025). "APOL1 G1 and G2 risk alleles are genetic risk factors for hypertension and more recently have been associated to the risk of developing preeclampsia." (PMID 39496047, 2024). "Nonsynonymous variants coded by G1 and the coding region deletion G2 in APOL1 are sequence variants that have strong relationships to focal segmental glomerulosclerosis and hypertension-attributed end-stage kidney disease." (PMID 38017264, 2023). "In 2010, two studies on African Americans identified genetic variants, named G1 and G2 alleles, in the Apolipoprotein L1 (APOL1) gene associated with an increased risk of developing hypertension-attributed ESRD or FSGS." (PMID 36588788, 2022). "APOL1*SNP interactions that met the threshold of 1.0 × 10−5 were replicated in the Genetics of Hypertension Associated Treatment (GenHAT) study (626 ESKD cases and 6,165 controls)." (PMID 36250097, 2022). "ApoL1 risk alleles was associated with higher systolic blood pressure and earlier hypertension diagnoses." (PMID 36551995, 2022). "Participants with APOL1 high-risk genotypes had lower eGFR and higher levels of proteinuria and albuminuria and were more likely to have hypertension." (PMID 35497797, 2022). "APOL1 is one of the most widely examined genes that is associated with hypertension‐induced renal injury." (PMID 33377622, 2021). "APOL1 risk alleles are associated with higher systolic blood pressure and earlier hypertension diagnoses in young Afro-Americans." (PMID 31929905, 2019). "Case and control pairs (N = 15x2) were selected from those without diabetes and were matched for age, sex, body mass index, APOL1 risk allele count, and hypertension medication use." (PMID 28771472, 2017). "Such failure can be caused by many factors including drugoverdoses, crush syndrome, uncontrolled hypertension, long-term diabetes, and geneticpredisposition such as that caused by APOL1 mutation." (PMID 26628394, 2016). "Can screening for genetic mutations or APOL1 variants in childhood onset NS stratify those children at highest risk for hypertension and renal disease in adulthood?" (PMID 27252935, 2016). "In our study, for example, we found that only about a third of individuals with elevated ACR had high-risk APOL1 variants, however, the overwhelming majority had hypertension." (PMID 25884165, 2015). "A recent study showed that, among those of recent African ancestry, focal segmental glomerulosclerosis and hypertension-attributed ESRD are strongly associated with two coding sequence variants in the APOL1 gene on chromosome 22." (PMID 23110237, 2012). "Hypertension linked to kidney diseases poses a more significant challenge among Black individuals when compared to other ethnicities, and a substantial part of this inequality can be attributed to genetic variations in the APOL1 gene." (PMID 38012593, 2023).
Hypertension (continued). "APOL1 high risk genotype and traditional risk factors (e.g., hypertension, diabetes, smoking) do not fully explain the high rates of albuminuria in the R3 study population, although hypertension is likely to be a significant contributing factor." (PMID 35787257, 2022). "Our study comprises the largest cohort of Black participants in which the association between GSTM1 status and CKD has been explored; the GSTM1 groups were indistinguishable in terms of HIV parameters and relevant comorbidities, such as hypertension and diabetes, and APOL1 renal risk status." (PMID 35967115, 2022). "Disclosing APOL1 genetic testing results to patients of African ancestry with hypertension and to their clinicians was associated with a greater reduction in blood pressure, kidney disease screening, and self-reported behavior changes in those with high-risk APOL1 genotypes." (PMID 35244702, 2022). "In 2010, Giulio Genovese and his colleagues reported that two independent sequence variants G1 and G2 in APOL1 were associated with a higher risk of developing hypertension‐induced kidney disease in an African‐American population than in the patients of European descent." (PMID 33377622, 2021). "The APOL1 gene has been shown to be independently associated with hypertension and CKD." (PMID 34671490, 2021). "Although some of this increased risk may be attributable to the increased prevalence of hypertension as well as to socioeconomic factors, there is increasing evidence that variants in the gene encoding apolipoprotein L1 (APOL1) might play a contributory role." (PMID 31897715, 2021). "Additionally, APOL1 increases the vulnerability of podocytes to injury in response to oxidative stress associated with hypertension." (PMID 33377622, 2021). "The duration of hypertension was greater in individuals with a single APOL1 risk variant." (PMID 31532792, 2019). "Second, APOL1 variants contribute to hypertension and to a second hit which leads to CKD." (PMID 31929905, 2019). "This may reflect underdiagnosis, a younger cohort, local ART prescribing patterns, and variation in the prevalence of comorbid risk factors for kidney disease including hepatitis virus infection, APOL1 polymorphisms, hypertension and diabetes mellitus." (PMID 31596867, 2019). "Hypertension-attributed renal failure in this group has been strongly linked with the ApoL1 gene." (PMID 24985953, 2014). "Although Stage 1 or 2 hypertension and exposure to potentially nephrotoxic antiretroviral medications were common in R3 participants, other traditional risk factors for albuminuria and kidney disease, including diabetes, APOL1 high-risk genotype, and smoking were rare." (PMID 35787257, 2022). "Multiple studies have identified diabetes and hypertension as key drivers of CKD burden in the region, while recent evidence also implicates APOL1 risk alleles and environmental stressors in disease progression." (PMID 40971998, 2025). "The recognition of the role of APOL1-RRVs in the development of CKD was followed by reconsideration of the term hypertensive CKD in patients of African ancestry, with the connotation of hypertension as primarily causative for CKD." (PMID 40001508, 2025). "Proteins angiotensinogen (AGT), albumin (ALB), APOL1, and uromodulin (UMOD) were associated with CKD and hypertension with high disease scores of 5.0 (100% confidence), 4.0 (80%), 3.9 (78%), and 3.8 (76%), respectively." (PMID 38402394, 2024). "In the fully adjusted model,APOL1 high-risk genotypes (OR 2.1; 95% CI 1.3 - 3.4); HIV infection (OR 1.8; 1.1 - 2.8); hypertension (OR 2.8; 95% CI 1.8 - 4.3), and diabetes (OR 4.1; 95% CI 2.0 - 8.4) were risk factors." (PMID 36457874, 2022). "What are the effects of testing and disclosing the genetic results for APOL1 on patients of African ancestry with hypertension and their clinicians?" (PMID 35244702, 2022).